RN7SL622P (RNA, 7SL, cytoplasmic 622, pseudogene)
Gene: Miscellaneous RNA gene on chromosome 17 (67,977,698 to 67,977,972, forward strand). Ensembl gene ENSG00000265052.
Homologues: Paralogues in human: RN7SL488P (84% identical), RN7SL339P (83% identical), RN7SL96P (82% identical), RN7SL774P (82% identical), RN7SL811P (81% identical), Metazoa_SRP (81% identical), RN7SL391P (81% identical), RN7SL163P (80% identical), RN7SL510P (80% identical), Metazoa_SRP (80% identical), RN7SL474P (80% identical), RN7SL819P (80% identical), and 712 more.